BTG3 (BTG anti-proliferation factor 3)
Diseases named in the same sentence as BTG3 in open-access papers (continued):
Sharing a sentence is not in itself a finding about the gene and the disease.
cancer (continued). "In some human cancers, abnormal hypermethylation or histone modification in promotor of BTG3 has been reported." (PMID 34466474, 2019). "Different studies have demonstrated that B-cell translocation gene 3 (BTG3) plays a suppressive role in the progress of different cancers." (PMID 34466474, 2019). "Lack of normal cells and detection the rate of early and late apoptosis due to no access to flow cytometry device can be considered as a limitation in the present study.Down-regulation of BTG3 gene has been confirmed in several cancers." (PMID 34466474, 2019). "Previous studies have demonstrated that BTG3 expression is downregulated in many cancers, including prostate cancer, renal carcinoma, and hepatocellular carcinoma." (PMID 29270670, 2018). "In contrast, more frequent methylation of BTG3 was found in colorectal mucosa than cancer, similar to its mRNA, while versa for BTG3 immunopositivity." (PMID 28407690, 2017). "Altogether, the transcriptional expression levels of TOB1-2 and BTG2 were significantly reduced in most cancers compared with normal tissues, while BTG3 was upregulated in most cancers." (PMID 28922388, 2017). "We observed that the mRNA expression levels of TOB1-2 and BTG2 were decreased in most cancers compared with normal tissues, while BTG3 was upregulated in most cancers." (PMID 28922388, 2017). "Then we performed a pan-cancer bioinformatics analysis based on the BioXpress database, to analyze the mRNA expression of FBXL5 and BTG3 in cancer tissues and their paired normal tissues across multiple cancer types." (PMID 28399926, 2017). "The TSG BTG3 is a negative regulator of E2F-1 signaling and often silenced in prostate and other types of cancer by DNA hypermethylation." (PMID 25322458, 2014). "Well-differentiated carcinoma showed higher BTG3 mRNA expression in comparison with moderately and poorly differentiated ones (p < 0.05)." (PMID 23657964, 2013). "In the present study, BTG3 mRNA level was reduced from ovarian borderline tumor and carcinoma, in line with the immunohistochemical data." (PMID 23657964, 2013). "Here, we for the first time examined in situ BTG3 expression in ovarian normal tissue, benign and borderline tumor, and carcinoma samples." (PMID 23657964, 2013). "It was found that BTG3 protein was mainly localized in the cytoplasm of ovarian fiber cells, fallopian tube, benign and borderline tumor, and carcinoma cells." (PMID 23657964, 2013). "In agreement with their anti-proliferative activity, loss of expression of BTG2, BTG3, and TOB1 is frequently observed in clinical samples of various cancers, including lung, thyroid and breast tumours." (PMID 23236473, 2012). "Supporting a causal relationship between loss of expression and disease, gene inactivation of BTG3 and TOB1 is associated with predisposition to cancer in mouse models." (PMID 23236473, 2012). "Developing strategies to upregulate BTG3 expression or inhibit the activity of miR-106b-5p could represent novel treatment approaches for this aggressive form of cancer." (PMID 41155295, 2025). "Another miRNA, miR20b-5p, which was significantly downregulated by pembrolizumab treatment, was shown in other studies to be highly expressed in LC and targeting B cell translocation gene 3 (BTG3), thus downregulating BTG3 expression and leading to increased proliferation and cancer cell migration." (PMID 39766101, 2024). "This could support the findings that reduced levels of miR20b-5p in response to immunotherapy could rescue and restore BTG3 expression and reverse cancer cell migration and metastasis, showing a positive outcome for PD-1 blockade immunotherapy." (PMID 39766101, 2024). "Similarly, supplement with BTG3 protein suppressed the colony formation of cancer cells elevated by TRIM65 overexpression." (PMID 38777825, 2024). "BTG3 has been well identified as a tumor suppressor gene that could inhibit proliferation, migration and invasion in a variety of cancer types." (PMID 37904215, 2023).
cancer (continued). "Additionally, BTG3 methylation was negatively correlated with its mRNA expression, and was higher in cancer than in normal tissues of the stomach, lung, and breast." (PMID 36186486, 2022). "A negative association between BTG3 expression and relapse-free prognosis was observed in Luminal-B cancer patients (p < 0.05, data not shown)." (PMID 36186486, 2022). "BTG3 expression was higher in G3 than G2 carcinoma patients by UALCAN (p < 0.05)." (PMID 36186486, 2022). "BTG3 expression was higher in G1 than G3 carcinomas by UALCAN (p < 0.05)." (PMID 36186486, 2022). "Importantly, the high miR-20a expression and the correspondent low FBXL5 and BTG3 expression in cancer tissues correlate with the poor prognosis of the patients in a Kaplan–Meier survival analysis." (PMID 33803151, 2021). "The acquisition of EMT features represents a key contributor to chemoresistance in cervical cancer, thus the expression of the EMT repressors F-Box and Leucine Rich Repeat Protein 5 (FBXL5) and BTG Anti-Proliferation Factor 3 (BTG3) is retained low in cancer tissues and cisplatin-resistant cells." (PMID 33803151, 2021). "Moreover, analysis of clinical datasets revealed that a higher BTG3/VEGFA expression ratio correlates with improved patient survival in a number of cancer types." (PMID 33311481, 2020). "BTG3 has also been shown to be downregulated in several cancers, and its expression might predict survival and prognosis in cancer patients." (PMID 32093041, 2020). "BTG3 knockdown in CRC cells promoted cell proliferation, migration, and invasion, disturbed the cell cycle, and impaired apoptosis by regulating multiple genes and cancer-associated pathways." (PMID 29270670, 2018). "In this study, we also found that TOB1, BTG1 and BTG3 could be a prognostic marker or potential therapeutic target in several cancer types, consistent with previous reports." (PMID 28922388, 2017). "Moreover, we examined the expression of BTG3 mRNA and protein in CRCs, and compared them with clinicopathological parameters of cancers." (PMID 28407690, 2017). "In light of the important role of AKT in tumorigenesis, angiogenesis, and metastasis, the BTG3 peptide or its derivatives may serve as promising leads for cancer drug development." (PMID 25569101, 2015). "BTG3 mRNA expression was stronger in cancer than in the adjacent mucosa (p < 0.05)." (PMID 25904053, 2015). "BTG3 mRNA expression was detected by real-time RT–PCR in ovarian benign and malignant tumors." (PMID 23657964, 2013). "Recent evidence demonstrates that BTG3 plays a suppressive role in cancer progression." (PMID 24147003, 2013). "Moreover, studies have confirmed that the upregulation of the BTG3 gene in cancer cells could enhance the toxicity of chemotherapy drugs, including cisplatin and paclitaxel." (PMID 37904215, 2023). "In our previous studies, we demonstrated that BTG3 interacts with and suppresses AKT, a kinase that is frequently dysregulated in cancer." (PMID 38714880, 2024). "We used bioinformatics methods to analyze the characteristics of TOB1, TOB2, BTG1, BTG2, BTG3 and BTG4 in pan-cancer." (PMID 38062199, 2023). "GC represents one of the most influenced cancers through the PI3K/AKT pathway, thus arising an assumption that BTG3 is involved in the ERS-triggered apoptosis via the PI3K/AKT pathway." (PMID 36815904, 2023). "Through a series of bioinformatics analysis, the findings in our study supported the important role of TOB1, TOB2, BTG1, BTG2, BTG3 and BTG4 in pan-cancer and provided a reliable basis for detecting biomarkers of cancer." (PMID 38062199, 2023). "In the present study, we comprehensively analyzed the role of TOB1, TOB2, BTG1, BTG2, BTG3 and BTG4 in cancer from the perspective of bioinformatics." (PMID 38062199, 2023). "BTG3 is a member of the antiproliferative BTG gene family, and its downregulation has been observed in human cancers." (PMID 36544762, 2022).
cancer (continued). "We analyzed BTG3 expression using Oncomine, TCGA (the cancer genome atlas), Xiantao, UALCAN (The University of ALabama at Birmingham Cancer data analysis Portal) and Kaplan-Meier plotter databases." (PMID 36186486, 2022). "In this study, we evaluate the effect of genistein on BTG3 expression and proliferation of ALL cancer cells." (PMID 34466474, 2019). "PTEN, SOX6, WNK2, BTG3, and RBSP3 protein expression was decreased in miR-18a-overexpressing CC cells but was increased in miR-18a-silenced cancer cells." (PMID 29855617, 2018). "Here we present evidence that BTG3 binds and suppresses AKT, a kinase frequently deregulated in cancers." (PMID 25569101, 2015). "After treated with different anti-cancer agents (cisplatin, MG132, paclitaxel and SAHA), both BTG3 transfectants showed lower viability and higher apoptosis than the control in both time- and dose-dependent manners (p < 0.05)." (PMID 25904053, 2015). "To elucidate the role of BTG3 in the progression of HCC, we performed a series of assays to detect the effect of BTG3 over-expression on cancer cell proliferation, cell cycle transition and invasion in vitro." (PMID 24147003, 2013). "Cucurbitacin B, a triterpenoid isolated from the Cucurbitaceae family of plants, induced DNA demethylation in the promoter region of a TSG, B-cell translocation gene 3 (BTG3), thereby increasing its expression, resulting in the inhibition of cancer cell proliferation and stimulating cell apoptosis." (PMID 40239010, 2025). "There appeared to be a negative relationship between BTG3 expression and the progression-free survival rate of cancer patients with surgical margin negative or smoking cancer patients (p < 0.05, data not shown)." (PMID 36186486, 2022). "The down- regulated BTG3 expression was also found during ovarian carcinogenesis, and positively correlated with the dedifferentiation, FIGO staging, and adverse prognosis of cancers." (PMID 28407690, 2017). "Among these, FBXL5 and BTG3 have been reported to regulate EMT and cancer metastasis." (PMID 28399926, 2017). "This analysis also indicated a similar negative correlation between high iASPP and low FBXL5/BTG3 expression in various cancer types." (PMID 28399926, 2017). "BTG3 protein was more detected in colorectal non-neoplastic mucosa (NNM) than that in cancer (p<0.05)." (PMID 28407690, 2017). "Genistein could elevate BTG3 for 1.7 folds in MOLT4 and JURKAT and 2.7 folds in MOLT17 cell lines at transcription level conveged with 60 to 90% reduction in the proliferation rate of cancer cells." (PMID 34466474, 2019). "As cancer cells are frequently exposed to a hypoxic environment and are often under oxidative stress, it would be interesting to know how interaction between BTG3 and HIF-1α is regulated in normal, as opposed to cancer cells, under these conditions." (PMID 33311481, 2020).
benign tumor (2 papers, 2013). "Our findings are in agreement with the finding that BTG3 mRNA expression was higher in ovarian normal tissue and benign tumors than that in borderline, primary, and metastatic ovarian carcinoma." (PMID 24084718, 2013). "The expression of BTG3 protein was also evaluated in ovarian normal tissue, benign tumors, and EOCs by western blot." (PMID 23657964, 2013). "Using western blot, BTG3 protein was found lower in EOCs compared to the normal and benign tumors (p < 0.05), and poorly differentiated EOCs showed lower BTG3 expression than well-differentiated and moderately differentiated EOCs (p < 0.05)." (PMID 23657964, 2013). "Immunohistochemically, BTG3 protein expression was statistically lower in EOCs than normal tissue and benign tumors (p < 0.05)." (PMID 23657964, 2013).
colorectal (2 papers, 2017 to 2018). "To further clarify the roles of BTG3 in colorectal carcinogenesis and progression, we evaluated the effects of downregulating BTG3 on cell proliferation, the cell cycle, and apoptosis." (PMID 29270670, 2018). "In summary, down-regulated BTG3 expression might be positively correlated with the malignant transformation of colorectal epithelial cells and should be considered as a good biomarker for colorectal carcinogenesis." (PMID 28407690, 2017).
inflammation (1 paper, 2020). Aberrant reaction of the microcirculation characterized by movement of fluid and leukocytes from the blood into extravascular tissues. "Furthermore, various levels of increase were observed among the 80 cytokines/growth factors examined upon BTG3 depletion, many of which are involved in chronic inflammation in vivo." (PMID 33311481, 2020).
BTG3 also shares sentences with these, for which no sentence is quoted: adenocarcinoma (2 papers); esophageal adenocarcinoma (2); Autoimmunity (1); basal cell carcinoma (1); cervical squamous cell carcinoma (1); cognitive decline (1); epilepsy (1); gallstones (1); hematological malignancies (1); hepatitis C (1); HIV-1 infection (1); melanoma (1); Neurodevelopmental delay (1); neurological disorders (1); neurovascular disorder (1); oral cancer (1); pancreatic cancers (1); prostate intraepithelial neoplasia (1); psoriasis (1); rectal cancer (1); rectal mucinous adenocarcinoma (1); scleroderma (1); signet ring cell carcinoma (1); viral infection (1).